IL10 (interleukin 10)
Diseases named in the same sentence as IL10 in open-access papers (continued):
Sharing a sentence is not in itself a finding about the gene and the disease.
tumor (continued). "Additionally, the researchers have found a positive correlation between IL-10 levels in serum and tumor progression, which shows that IL-10 has an important influence on promoting the development of tumors." (PMID 32161718, 2020). "Thus, they hamper the tumor-killing immune effect during tumor progression, significantly overproducing IL-10 while decreasing IL-12." (PMID 33505964, 2020). "In addition, tumor infiltrated M2 macrophages exhibit a tumorigenic effect by producing high levels of IL-10 and TGF-β1." (PMID 32408477, 2020). "Several studies have found that IL-10 has both pro- and anti-tumor effects." (PMID 32283655, 2020). "Not only that, various studies have shown that IL-10 can promote the development of tumor cells." (PMID 33154947, 2020). "Over-production of immunosuppressive cytokines such as transforming growth factor (TGF-β) and IL-10 by tumor cells specially during tumor growth may suppress different effector pathways of the immune response." (PMID 31938023, 2020). "Therefore, in the tumour microenvironment IL-10 and IFN-γ are generally seen as mutually antagonist cytokines." (PMID 32397484, 2020). "IL10 could be produced either by the tumour cells themselves or by tumour elicitation of tumour-infiltrating, IL10 producing immune cells." (PMID 32802517, 2020). "Moreover, antigen presentation and dendritic cell (DC) activity were also mediated by IL-10, which was also identified as another major approach by which IL-10 participated in preventing anti-tumor responses in the TME." (PMID 32391256, 2020). "Recent studies have found that IL-10 and IL-35 produced by intratumoral Tregs cooperatively share a common BLIMP1 axis to promote the exhausted intratumoral T cell state and anti-tumor immunity, implying IL-10 and IL-35 contribute to maintaining immune tolerance." (PMID 32676072, 2020). "Female tumours had elevated IL-10+ macrophages, which correlated with survival." (PMID 32451467, 2020). "More importantly, BMP6 signaling could activate myeloid-derived suppressor cells (MDSCs) to secrete IL10 and could promote the differentiation of M2 macrophages, which could enhance the invasion and metastasis of tumor cells." (PMID 32195173, 2020). "Nevertheless, there is ample evidence to support that IL-10 has potent anti-tumor effects as well." (PMID 33614473, 2020). "In conclusion, we have identified a novel mechanism through which (tumor-induced) IL-10 paralyzes host anti-tumor immunity by blocking thymic DN2a cells along a T-cell fate pathway and altering the T-cell fate pathway by promoting the commitment of pro-T (DN2) toward DC lineage." (PMID 32582141, 2020). "Besides, Tumor-infiltrating B cells that express high levels of PD-L1, IL-10 and TGF-β repress the proliferation and activation of CD8+ T cells." (PMID 32973780, 2020). "Other studies have reported that macrophages could suppress the activity of anti-tumor immune cells and promote tumor progression, survival, and growth, as well as stimulate MDSCs to secrete the anti-inflammatory cytokine IL-10." (PMID 32784928, 2020). "When patients were classified by their IL-10 expression, differences appeared in tumor size." (PMID 32348468, 2020). "Our data indicate that Wnt5a could induce M2 polarization of TAMs by regulating CaKMII-ERK1/2-STAT3 pathway–mediated IL-10 secretion, ultimately promoting tumor growth and metastasis of CRC." (PMID 32228612, 2020). "IL-10 is an immunomodulatory cytokine, upregulated in various types of cancer; its correlation with the disease progression indicates a critical role in the tumour microenvironment." (PMID 32630302, 2020). "Interestingly, tumor-associated macrophages from patients with melanoma also activate GCN2 and IL-10 production in the tumor microenvironment." (PMID 33613560, 2020).
tumor (continued). "As the secretion of interleukins, especially IL‐10, are able to mediate an escape of tumor cells from the host immune system and inhibit NK‐cell mediated cytotoxicity, it could partly explain tumor recurrence and the poor prognosis associated with thoracotomy." (PMID 32985138, 2020). "Furthermore, MDSC and tumor cell cross-talk enhances IL-6 production within tumor microenvironment, while IL-10, produced by MDSCs, increases M2-like TAMs." (PMID 32824865, 2020). "Additionally, IL-10 can inhibit anti-tumour activity of NK cells, for example, by increasing the expression of non-classical MHC class I on tumour cells, given that non-classical MHC class I can inhibit NK cell activity." (PMID 32931721, 2020). "As found in preclinical studies, PD‐1 blockade immunotherapy could stimulate tumor‐infiltrating DCs to secrete IL‐10, which subsequently upregulated PD‐1 in a STAT‐3‐dependent manner on DCs, hence creating a vicious circle of immune escape." (PMID 32997401, 2020). "Crosstalk between tumor-derived EVs and macrophages can polarize them toward a more M2-like, pro-tumor TAM, which is associated with higher levels of the immunosuppressive cytokines IL10, IL4, and TGFβ." (PMID 32547552, 2020). "In conclusion, rlipoE7m plus POCpG/DOTAP combined could increase IL12p70 to promote Th1 responses and reduce IL-10 production to diminish immunosuppressive cells and alter the tumor microenvironment via intravenous immunization." (PMID 32231003, 2020). "Besides phenotypic maturation, further activation of moDCs was investigated by measuring their release of IL-12, IL-1β, and IL-10 after incubation with NB-PDT treated tumor supernatant." (PMID 32326519, 2020). "Therefore, we aimed to analyze the frequency of Breg cells among HCV-related HCC patients and studying its association with Treg cells, IL-10, IL-35, BAFF, and tumor progression." (PMID 32664587, 2020). "However, further studies are warranted to understand mechanistically how β-catenin regulates mTOR activation in tumor DCs to induce IL-10." (PMID 32132993, 2020). "Researchers indicated that TAMs are one of the M2‐like macrophages because of their high expression of anti‐inflammation marker genes, including IL‐10 (interleukin‐10) and IL‐1Rα (IL‐1 receptor alpha), which contribute highly towards growth of tumour and subsequent development." (PMID 32596949, 2020). "In addition, significantly higher levels of IL10 were found not only in the tumor itself, but also in the peritumoral tissue compared to control samples." (PMID 32100077, 2020). "In our experiments, the levels of IFN-γ and IL-10 were the highest in HO-1−/− mice, which suggests that these cytokines may facilitate tumor growth." (PMID 33287312, 2020). "Similarly, the combination of crizotinib and IL10 was more effective in inhibiting tumor proliferation, invasion, and metastasis compared to crizotinib alone (the concentration of IL10 was 1 mg/ml, and crizotinib was 1 μM)." (PMID 32724815, 2020). "M1-type macrophages secreting immunogenic cytokines, such as IL-12 and TNF-a, improve the immune response that exerts inhibitory effects on tumor growth, and M2-type macrophages secreting immunosuppressive cytokines, such as IL-10 and TGF-β, impair antitumor immunity to enhance tumor growth." (PMID 34138195, 2020). "Similar patterns may occur in single tumor cells, whereby enhanced IL-10 increases the percentage of Tregs." (PMID 32733437, 2020). "Stromal cells can mediate immune-suppression and protect tumor cells from cytotoxicity via secretion of soluble factors including immune suppressive mediators such as IL-10, TGF-β and PGE2 or growth factors such as stem cell factor (SCF), IL-7, IL-15, CXCL-12 among others." (PMID 32483120, 2020). "Importantly, systemic IL-10 levels correlate with the increase of the local tumor burden (T stage) and are also significantly in patients with distant metastasis." (PMID 32298379, 2020).
tumor (continued). "Furthermore, IL-10 is considered an immunosuppressive cytokine, which promotes tumor immune escape by reducing the anti-tumor immune responses in the tumor microenvironment." (PMID 32547401, 2020). "Furthermore, many tumor cells release cytokines, chemokines, and growth factors that recruit and induce FOXP3+ Tregs, and induce MDSCs and macrophages to release Th2 cytokines such as Tgf-β, IL-4, IL-10, and IL-13 which suppress anti-tumor immunity." (PMID 32508830, 2020). "Furthermore, TLR2 activation stimulates MDSCs to produce IL-10, which induces macrophage polarization toward the M2 tumor-promoting phenotype, while MDSC-produced IL-6 promotes tumor metastatic growth." (PMID 33321934, 2020). "The aim of this study is to investigate whether IL-10 interferes with tumor immunity in PTC with concomitant HT." (PMID 32348468, 2020). "However, in the tumor microenvironment, the high secretion of IL-10 and TGF-β by tumor-infiltrating Treg cells can facilitate tumor growth and invasion." (PMID 32595757, 2020). "[Apiaceae]) could downregulate the protein levels of indoleamine 2,3-dioxygenase, TGF-β, and IL-10, which promoted tumor infiltration and killing capability of NK cells to LLC (Lewis lung cancer) in mice." (PMID 32733246, 2020). "Importantly, intratumoral depletion of B cells or IL-10 blockade rendered AdjFluVx the ability to reduce tumor growth." (PMID 31888983, 2020). "In addition, the protective function of dendritic cells in stimulating the anti-tumor response is blunted by tumor factors that inhibit dendritic cell maturation and function such as PD-1 expression and release of IL-10, TGF-β1, arginase-1, and IDO." (PMID 33371456, 2020). "The IL-10 inhibits NF-kB; therefore, this may downregulate the expression of pro-inflammatory cytokines and act as an anti-tumor cytokine." (PMID 32283655, 2020). "Attenuated expression of IL-10 may alleviate immunosuppression of other myeloid effector cells, as TAM-derived IL-10 has been shown to inhibit IL-12 production in intratumoral dendritic cells, leading to suppression of anti-tumor CD8+ T cell activation." (PMID 32300202, 2020). "In summary, the study shows that IL10 can inhibit the growth of transplanted tumor in vivo and the main mechanism may be the IL10-medited indirect inhibition of pro- inflammatory cytokines IL6 and TNF-α secretion and tumor angiogenesis." (PMID 32742480, 2020). "In the tumor microenvironment, hyperactive Tregs could inhibit the tumor-killing activity of effector cells by secreting cytokines such as interleukin-10 (IL-10) and TGF-β." (PMID 32222150, 2020). "Alternatively activated M2 macrophages regulate anti-inflammation and reduce NO and reactive oxygen species (ROS) levels but induce Arginase-1, anti-inflammatory cytokines (such as TGF-β, IL-10 and IL-6) and growth factors that support neoplasia and induce tumor cell movement." (PMID 32059469, 2020). "Absent or present in small concentrations in physiological conditions, they are recruited by tumor cells or by inflammatory stimuli and are responsible for the production of several factors involved in tumor growth and immune evasion, such as IL-10, TGF-β, and VEGF." (PMID 33036192, 2020). "TAMs in mouse and human cancers largely express molecules associated with M2-like phenotypes that include arginase (ARG1), interleukin-10 (IL-10), and transforming growth factor β (TGFβ), which induce immunosuppression and fibrosis within the tumor microenvironment." (PMID 33374253, 2020). "Finally, tumor cells produce Csf1 and IL-34 which recruit immunosuppressive Csf1r+ TAMs that produce IL-6, IL-10, and TGFβ, all factors that promote a cycle of immune suppression." (PMID 33584701, 2020). "The role of IL10 on the local anti-tumor response remains to be elucidated." (PMID 32353988, 2020).
tumor (continued). "Additionally, MSC2-sourced TGF-β and IL-10 downregulate production of inflammatory cytokines and reduce cytotoxicity of Th1 and Th17 cells and CTLs, contributing to the enhanced tumor growth and progression." (PMID 32695181, 2020). "Collectively, HJ901 treatment may have reduced IL-6 and IL-10 secretion in cells and suppressed cell proliferation and tumor growth in cells and mice through possible mechanisms that modulate the TLR7/9, NF-κB, and JAK2-STAT3 signaling pathways." (PMID 32391356, 2020). "Moreover, myeloid-restricted Stat3 deletion leads to enhanced production of IL-12 and reduced expression of tumor-promoting cytokines such as IL-23 and IL-10." (PMID 31947933, 2020). "Along with the crosstalk between tumor plasma cells and BM niche cells, a high concentration of immunosuppressive factors including TGF-β, IL-10, IL-6, and prostaglandin E2 in the MM BM microenvironment promotes tumor propagation and survival and at the same time generates great immune dysfunction." (PMID 33194767, 2020). "Importantly, eosinophil-derived cytokines such as IL-12 and IL-10, can also decrease metastasis by enhancing E-cadherin expression on tumor cells and improving their adhesion." (PMID 33233582, 2020). "Our results indicated that M2-polarized macrophages induced by ICC promote tumor growth and invasiveness through IL-10/STAT3-induced EMT and might be a potential therapeutic target for ICC." (PMID 33372604, 2020). "In addition, a pegylated form of IL-10, with increased half-life compared to recombinant IL-10, activates anti-tumor CD8+ T cells in humans." (PMID 31947933, 2020). "Notably, caerin peptides were able to increase the survival time of TC-1 tumor bearing mice after therapeutic vaccination with a HPV16E7 peptide-based vaccine containing IL-10 inhibitor, via recruiting increased amounts of T cells to the tumor site." (PMID 32850805, 2020). "IL-10 plays multiple roles for immunosuppression in the tumor microenvironment." (PMID 32231003, 2020). "Moreover, there is evidence that secretion of IL-10 from cancer stem cells reduces the proliferation of T cells and promotes tumor progression." (PMID 33426090, 2020). "Besides, inhibitory regulatory T cells (Tregs) are also associated with the tumor progression; for example, Treg secretes inhibitory cytokines, such as TGF-β and IL-10, and expresses cytotoxic T lymphocyte-associated protein 4 (CTLA4)." (PMID 33490233, 2020). "In extended studies, we determined that another important contributor to tumor-induced T-cell developmental arrest is IL-10, whose expression was upregulated in the thymus, particularly that of the tumor-bearing host, particularly at the thymic CMJ where DN2 T cells tend to accumulate." (PMID 32582141, 2020). "Elevation of IL-10 level could facilitate the development of cancer by supporting tumour cell escape from host immune response via activation of PRL-R variants with altered pro-inflammatory or abrogated function." (PMID 30947706, 2019). "In the pancreatic cancer model, STING could be stimulated by the tumor antigen released after radiotherapy, or the artificial agonist that blocks M2 macrophage differentiation and decreases IL-10 secretion, and control local and distant tumors." (PMID 31708918, 2019). "Tumor microenvironment inflammatory cells (e.g., immune cells, fibroblasts, and endothelial cells), but also cancer cells, are known to produce and secrete several cytokines, such as IL-6, IL-10, IL-13, VEGF, and TGFβ." (PMID 30764482, 2019). "Also, IL-10 contributes to poor prognosis, worse tumor staging and low anti-tumor immunity in patients with unresectable HCC." (PMID 31653148, 2019). "Tumor-derived immunosuppressive cytokines, like IL-10 and exosomes, have been noted." (PMID 35582715, 2019).
tumor (continued). "To assess the proportion of Bregs in the OPSCC tumor microenvironment, we analyzed the level of IL-10 secreting TIL-Bs after 5 and 24 h of stimulation with CpG ODN 2006 and CD40L in the presence of PMA, ionomycin and brefeldin A using flow cytometry (Cohort 3)." (PMID 31623665, 2019). "Interleukin-10 is a cytokine with a strong immunosuppressive effect, because it inhibits the proinflammatory action of Th1 lymphocytes and may favor tumor growth in vitro by stimulating cell proliferation and inhibiting apoptosis." (PMID 31886296, 2019). "We hypothesize that neutralization of IL-10 in conjunction with production of type I interferons (IFNs) – induced by 2′3’-cGAMP-mediated activation of the STING pathway – reverses the tumor microenvironment from immunosuppressive to immunostimulatory." (PMID 31362778, 2019). "Similar to TGFβ, IL-10 and IL-4 have dynamic effects on tumor promotion and progression." (PMID 31174326, 2019). "Interestingly, poly A:U decreased by half the density of M2-like macrophages producing IL10 inside the tumor bed, and at the same time expanded the number of monocyte-derived cells producing TNF, particularly among those that did not express MHCII." (PMID 30949170, 2019). "Here, we have revealed a TRAPs-mediated regulatory mechanism of CD4+ T cells differentiation whereby HSP90α on the surface of TRAPs educate CD4+ T cells via a TLR2–autocrine IL-6 cascade to express IL-10 and IL-21 and engender immune suppression to promote tumor growth and metastasis." (PMID 31300052, 2019). "Thus, all of these findings suggest that C‐6‐S can be a significant promoter of the anti‐inflammatory activity of IL‐10 in the tumor microenvironment, thereby preventing the initiation of a tumor or supporting the progression of an established tumor." (PMID 30637950, 2019). "In addition to tumor cell-derived factors, T helper 2 (Th2) cytokines such as IL-4, IL-10, and IL-13 also promote the differentiation of TAMs, whereas Th1 cytokines have an inhibitory role." (PMID 31428574, 2019). "Thus, the high expression of PD1 on CD8+ TILs is associated with the compromised ability to produce pro-inflammatory cytokines and inferior anti-tumor activity but with the increased capacity to secrete immunosuppressive cytokine IL-10." (PMID 31783783, 2019). "This indicated that PD-L1 expression in macrophages could be regulated by IL-10, while the secretion of IL-10 by macrophages could in turn be regulated by the tumor." (PMID 31781673, 2019). "Overall, we found that the absence of B cells and a tumor which more often classifies as an IL10 regulatory B cell were associated with a lack of response to anti-CTLA4 therapy." (PMID 31138334, 2019). "The strong accumulation of potential immunosupressive ARG+/IDO+/IL10+/TGF-β+M-/ PMN-MDSCs may be tumor-progression independent and may pose a significant impediment to the efficacy of anti-tumor responses elicited by (immuno)therapy." (PMID 31001284, 2019). "Additionally, CD4 + CD25 + Treg cells secrete TGF-β and IL-10 to suppress effector T cells such as CD8 + cytotoxic T lymphocytes infiltrating the tumor into HCC secreting anti-tumor effector molecules such as IFN -γ, IL-2 and TNFα." (PMID 31600917, 2019). "The main mechanisms that eliminate tumor cells in CRC are gamma IFN and TNF (α and β) producing CD4 + TH1 cells and IL10 secreted by FoxP3+ regulatory T cells by NK or γδ T cells that suppress or downregulate induction and proliferation of effector T cells at the tumor site." (PMID 31303863, 2019). "In the current study, however, HPV16 E7 peptide-based vaccine was unable to prolong the survival time of TC-1 tumour bearing mice when IL-10 signalling was blocked through subcutaneously administration of anti-IL-10 receptor antibodies at the time of immunisation." (PMID 31277636, 2019).